TFF2 (trefoil factor 2)
Diseases named in the same sentence as TFF2 in open-access papers (continued):
Sharing a sentence is not in itself a finding about the gene and the disease.
cancer (continued). "In addition, our data are consistent with previously published work that showed that TFF1 and TFF2 are frequently overexpressed in several human cancers." (PMID 31216714, 2019). "Suppression of cancer by TFF2 was abrogated following surgical disruption of vagal innervation." (PMID 26841680, 2016). "TFF2 offers a potential approach to prevent and to treat cancer." (PMID 26841680, 2016). "Having established splenic TFF2 as an important factor within the vagally mediated anti-inflammatory reflex arc, we wondered whether exogenous TFF2 delivery could be used to suppress MDSCs and cancer." (PMID 26841680, 2016). "For instance, in LCRC, researchers have identified a subgroup of cancer cells enriched for genes involved in maintaining of the gut lining (e.g., TFF1, TFF2, AGR3, MUC5AC)." (PMID 41450739, 2025). "TFF1, TFF2, and MUC5AC were highly expressed in foveolar cells-1 and -2, intestinal metaplasia cells, and cancer cell cluster EAC-01." (PMID 40925382, 2025). "For example, TFF2 weakly enhanced the chemotaxis of bronchial BEAS-2B cells, as well as pancreatic cell lines, and inhibited apoptosis in several cancer cell lines and pancreatic explant cultures." (PMID 37108221, 2023). "In Elyada’s scRNA-seq analysis, ductal cancer cells in human PDAC were clustered in two major subtypes: the classic (by TFF1, TFF2, LYZ, VSIG2, and CEACAM6 marker genes) and secretory (by SPP1, CLU, CTGF, and COL18A1 marker genes) subtypes." (PMID 34035226, 2021). "Previous studies showed that TFF2 exerts its mitogenic effect through the CXCR4 signaling pathway in pancreatic beta cells and several other cancer cell lines." (PMID 34146542, 2021). "We probed the cancer genome atlas database and found a similar trend in HCC: patients with higher expression of Tff2 showed a lower survival rate." (PMID 34146542, 2021). "For practical use of serum TFF1, TFF2, and TFF3 for cancer screening, subjects who were detected to have high serum TFF3, should be scrutinized by imaging examination." (PMID 28687783, 2017). "TFF2 suppresses IMC/MDSC proliferation in part through downregulation of cyclin D1 (and possibly through upregulation of cell-bound ApoE) thus reducing MDSCs and liberating anti-tumorigenic CD8+ T cells to inhibit the development of cancer." (PMID 26841680, 2016). "Through analyzing the methylated DNA immunoprecipitation (MeDIP) sequencing profiles available from our center and The Cancer Genome Atlas (TCGA), we identified that cg01886855 (TFF1 MS) and cg26403416 (TFF2 MS) might be the key CpG island sites separately for the TFF1/TFF2 DNA methylation." (PMID 36428568, 2022). "Regarding the molecular and cellular pathways beyond such TFF2 metabolic roles, we highlight the receptor chemokine (C-X-C motif) receptor 4 (CXCR4), that belongs to the important family of G protein-coupled receptor, which is a known TFF2 receptor, including in cancer cell lines." (PMID 34944474, 2021).
infection (33 papers, 2008 to 2025). The state of being infected such as from the introduction of a foreign agent such as serum, vaccine, antigenic substance or organism. "In the lung, a significant upregulation in the mRNA expression of the gel-forming mucins, Muc5ac and Muc5b, trefoil factors, Tff1 and Tff2, and Relm-β, was observed in the acute infection phase." (PMID 39596084, 2024). "Our study revealed that morbillivirus triggers massive upregulation of TFF1, TFF3 and, to a lesser degree, TFF2 expression, provided infection occurred during lung immune homeostasis." (PMID 38331906, 2024). "In this regard, TFF2-IFN is likely to not only have an effect in the early stage of infection, but also be applicable in the late stage of infection, and further exploration will be worthwhile in the clinic in the future." (PMID 36578554, 2022). "In contrast, infection with the blood fluke S. haematobium decreased TFF2 and TFF3 levels in serum of infected Nigerian children, also with some evidence of age-dependence." (PMID 34662329, 2021). "In contrast, after injury or infection, TFF2 has diverse roles in the immune system and for inflammation." (PMID 34066339, 2021). "qRT-PCR results showed an increased expression of GC genes abl1 and tff-2 in infection-IV in comparison to infection-I and -II, whereas the expression of gankyrin was significantly higher in infection-III and -IV than in infection-I and -II." (PMID 34585958, 2021). "We found that serum levels of TFF2 and 3 were reduced by infection, likely in an age dependent manner." (PMID 34662329, 2021). "In the 2-way ANOVA, sex was not significant (F = 0.93 p = 0.3382), but there was a significant sex by cohort interaction (F = 2.70 p = 0.0342), indicating that the effect of infection on TFF2 levels is dependent on sex." (PMID 34662329, 2021). "There was a strong association of age with serum levels of TFF2 and TFF3, and but the sample size within the infected and uninfected age groups restricted a formal analysis of age and infection interaction." (PMID 34662329, 2021). "Since liver shows the highest level of transgene expression following infection with adenovirus, we first confirmed TFF2 mRNA expression in the liver of Tff2-null mice after a single dose (5 × 108 pfu per mouse) of Ad-Tff2-CTP-Flag versus Ad-Tff2." (PMID 30042499, 2019). "TFF1 and TFF2 are up-regulated upon infection, in both doxycycline-induced and -uninduced cells, but their levels are significantly higher in TFF1 hyper-expressing cells (dox-induced)." (PMID 29085807, 2017). "The other two members of the Trefoil Factor Family are both induced up to 5 days post-infection; then, their expression is back to basal levels and only TFF2 is again up-regulated at 6 weeks." (PMID 29085807, 2017). "Regarding the other two members of the family, we measured an up-regulation (up to 2 to 3-fold) at earlier time of infection and different behaviors after 6 weeks when TFF2 keeps increasing, while TFF3 levels is lower." (PMID 29085807, 2017). "For example, the expression of CFI, CXCR6, LGALS15, and MMP1 was significantly upregulated while TFF2 mRNA level was significantly repressed by infection only in the resistant breed (CHB), in a good agreement with the RNAseq analysis." (PMID 27197554, 2016). "Interestingly, the TFF2 protein is involved in intestinal defence and repair mechanisms, while TFF2 overexpression is often observed in the case of significant tissue damage, infection or neoplastic changes in the within the digestive tract." (PMID 37049430, 2023). "However, there was a significant effect of infection on both TFF2 (F = 3.23 p = 0.015) and TFF3 after transformation (F = 12.04, p <0.0001), but not on IL-33 levels after transformation (F = 1.88 p = 0.1031)." (PMID 34662329, 2021). "TFF2 also serves as mucosal healers via protecting mucosal damage, promoting cell motility, and alveolar type 2 cell proliferation, and restores pulmonary gas exchange after infection." (PMID 32849610, 2020).
infection (continued). "TFF2 also induces IL-25 and IL-33 after infection to induce type 2 immunity and repair." (PMID 32849610, 2020). "Infection with Helicobacter pylori or chemical injury leads to induction of metaplastic cell lineages, notably the appearance of abnormal mucus-producing cells at the base of the gastric glands, known as spasmolytic polypeptide/trefoil factor 2-expressing metaplasia (SPEM)." (PMID 34208872, 2021). "A reduction in expression of tff-2 was observed at 12 and 24 h in infection-III and -IV compared to infection-I and -II." (PMID 34585958, 2021). "Given that TFF2 is low in younger populations and further reduced in S. haematobium infected children, this could possibly explain why TNFα is high in urine and by proxy the infection site of the bladder and urinary tract, where S. haematobium eggs emerge from tissue into the urine." (PMID 34662329, 2021). "Similar to our discussion for TFF2, it is also possible that the disruption is a result of the initial infection which does not heal due to the chronic infection." (PMID 39561211, 2024). "Also, in 48-h-postinfection infection-III and -IV samples increased expression of tff-2 was noticed." (PMID 34585958, 2021). "On the one hand, TFF2 is a brake for myeloid cells (e.g., inhibition of IL-6 and IL-12 release) so that, in particular, Th1 inflammation after a mucosal challenge (infection) is not overshooting (anti-inflammatory effect)." (PMID 34066339, 2021). "The results of GEO dataset (GSE74577) indicated that the expression of MUC1 but not TFF2 was significantly decreased in GES-1 cells after 24-h infection with H. pylori (P = 4.49 × 10− 4, P = 0.582, respectively)." (PMID 32122390, 2020). "The result demonstrated significantly positive correlation of MUC1 and TFF2 expression among GC patients with H. pylori infection but not for those without infection (total: r = 0.287, P = 0.028; H. pylori negative: r = 0.196, P = 0.318; H. pylori positive: r = 0.382, P = 0.034)." (PMID 32122390, 2020). "Moreover, the presence of TFF1 might influence the regulation of TFF2 and TFF3 expression upon infection, since TFF2 turns to be more induced than expected, while TFF3 is not." (PMID 29085807, 2017). "Before infection, the non-carriers had significantly (P < 0.05) elevated levels of ITLN-2, TFF2, and Ovar-Gal14 compared to the carriers." (PMID 21385411, 2011). "In particular, the expression of IL13 and RETNLB was significantly increased in infected pigs, regardless of diet (main effect of infection with a fold change of 3.7 and 1.7, respectively), and the expression of CCL26, IL10 and TFF2 also tended to be increased." (PMID 38081984, 2023).
adenocarcinoma (4 papers, 2012 to 2023). A common cancer characterized by the presence of malignant glandular cells. "In conclusion, decreased αGlcNAc glycosylation on the MUC6 scaffold protein also decreases TFF2 levels in that complex and could serve as an indicator of relatively high-grade PGA progressing to adenocarcinoma." (PMID 38062108, 2023).
colon (3 papers, 2015 to 2019). "In our recent research, TFF2 has been shown to promote epithelial cell migration and wound healing via PAR4 involved phosphorylation of ERK1/2, but the detail functions and molecular mechanisms of PAR4 and TFF2 in the progression of gastrointestinal tumor have not been discovered." (PMID 25876034, 2015).
kidney disease (2 papers, 2017 to 2020). "Even though patient number within renal diseases is low, this finding allows a first insight into differently regulated TFF2 expression rates within various CKD entities." (PMID 28355260, 2017). "Indeed, we were able to demonstrate higher TFF2 urine levels during early kidney diseases and that normalization of TFF2 serum levels is facilitated by increased fractional excretion." (PMID 28355260, 2017). "Our study was initially designed to evaluate TFF2 levels irrespective of the underlying kidney disease." (PMID 28355260, 2017). "Consequently, higher urinary TFF1 levels and the potentially co-regulated TFF2 might reflect the initial acute phase of renal diseases." (PMID 28355260, 2017). "Furthermore, histological examinations could identify the source of TFF2 expression in the affected kidney which in turn could help to understand the regulation of repair mechanisms within kidney diseases." (PMID 28355260, 2017).
benign tumors (1 paper, 2024). "As TFF3 is more abundant than the other two proteins (TFF2 is usually undetectable, and TFF1 was significantly more expressed in benign tumors), we mainly focused on TFF3 expression in this study." (PMID 39256888, 2024).
gastrointestinal disease (1 paper, 2017). A disease that occurs in the gastrointestinal system, excluding the hepatobiliary system. "In animal models TFF1 and TFF2, but not TFF3 have been shown to be upregulated during the acute phase of gastrointestinal diseases, while TFF3 reemerged during the restitution phase." (PMID 28355260, 2017).
hepatobiliary disorder (1 paper, 2023). A non-neoplastic or neoplastic disorder that affects the liver, bile ducts, and gallbladder. "On the other hand, the increased presence of trefoil factor 2 in dogs with evidence of different hepatobiliary disorders may suggest a potential role for this protein in such conditions." (PMID 37508119, 2023).
TFF2 also shares sentences with these, for which no sentence is quoted: Atrophy (2 papers); chronic atrophic gastritis (2); chronic obstructive pulmonary disease (2); gastric adenocarcinoma (2); respiratory syncytial virus infection (2); Sepsis (2); acute respiratory distress syndrome (1); allergic bronchopulmonary aspergillosis (1); ampullary carcinoma (1); amyloid (1); Anxiety (1); aortic stenosis (1); atherosclerosis (1); atopic dermatitis (1); Autoimmunity (1); bacterial infection (1); bladder cancer (1); breast tumors (1); carcinoma in situ (1); cardiomyopathy (1); cardiovascular disease (1); Cognitive impairment (1); colorectal adenocarcinoma (1); duodenal adenocarcinoma (1); ear tumor (1); early-onset retinal dystrophy (1); endometrial cancer (1); endometrioid carcinoma (1); Familial exudative vitreoretinopathy (1); fungal infection (1).
A further 42 diseases each share a sentence with TFF2 in 1 paper.